IL18R1 (interleukin 18 receptor 1)
Diseases named in the same sentence as IL18R1 in open-access papers (continued):
Sharing a sentence is not in itself a finding about the gene and the disease.
Sepsis (7 papers, 2014 to 2023). Sepsis is defined as life-threatening organ dysfunction caused by a dysregulated host response to infection. "As shown in these figures, the expression levels of RETN, S100A12, IL18R1, and KL were higher in the sepsis group, while that of GZMB, HLA-DPA1, CD3E, IL2RB, CD3G, and CCR3 were higher in the normal group (p < 0.05)." (PMID 38124071, 2023). "Our findings showed that the expression of RETN, S100A12, IL18R1, and KL was higher in the sepsis group, while the expression of GZMB, HLA-DPA1, CD3E, IL2RB, CD3G, and CCR3 was higher in the control group." (PMID 38124071, 2023). "Supporting the significance of the inflammasome in sepsis survivors, they also exhibited increased expression of genes downstream from inflammasome activation including interleukin-1 receptor 2 (IL1R2), IL18R1, and the IL-18 receptor accessory protein (IL18RAP)." (PMID 25538794, 2014).
malaria (6 papers, 2018 to 2024). Malaria is a serious and sometimes fatal disease caused by a parasite that commonly infects a certain type of mosquito which feeds on humans. "Immune-related genes TLR2 in Malaria and Legionellosis and IL-18 and IL18R1 in the TNF signaling pathway were upregulated in the LG compared to in the BG (p < 0.05)." (PMID 35268235, 2022). "TLR2 in Malaria and Legionellosis and IL-18 and IL18R1 in the TNF signaling pathway were upregulated in the LG compared to in the BG (p < 0.05)." (PMID 35268235, 2022).
celiac disease (5 papers, 2015 to 2026). An autoimmune genetic disorder with an unknown pattern of inheritance that primarily affects the digestive tract. "On the other hand, association evidence for RGS21, IL18R1, PLEK, CCR9, TAGAP was only found for celiac disease." (PMID 27015091, 2016). "We found 54 single-nucleotide polymorphisms (SNPs) in 5 genes associated with celiac disease (TAGAP, IL18R1, RGS21, PLEK, and CCR9) in time to celiac disease analyses (10−4>P>5.8x10−6)." (PMID 27015091, 2016). "However, confirmatory evidence (p<10−4) was found for SNPs in five regions previously reported to be associated with celiac disease (TAGAP, IL18R1, RGS21, PLEK, and CCR9)." (PMID 27015091, 2016).
parasitemia (5 papers, 2017 to 2024). "(A and C) Survival; (B and D) mean parasitemia levels at day 9 pi of Il18r1−/− (A and B) or Myd88−/− mice (C and D), which received or not 1.3 × 106 CD4+ T cells purified from infected WT B6 mice." (PMID 28895840, 2017). "Although in transferred Myd88−/− mice parasitemia was decreased to the WT level (as in transferred Il18r1−/−mice) and survival was also significantly delayed, still, the totality of Myd88−/− mice succumbed to infection." (PMID 28895840, 2017). "Furthermore, the adoptive transfer of WT CD4+ T cells was able to reduce parasitemia to WT levels in both Il18r1−/− and Myd88−/− infected mice, in an IFN-γ-dependent way, and to improve survival in both strain." (PMID 28895840, 2017). "WT mice presented significantly lower parasitemia when compared to either Il18r1−/− or Myd88−/− mice at day 9 pi, when the peak of parasites in the blood is attained, and no statistical difference in parasitemia levels was found between Il18r1−/− and Myd88−/− mice." (PMID 28895840, 2017). "To verify the impact of the absence of IL-18R- or MyD88-mediated signaling on resistance to infection, we compared parasitemia levels, as well as survival and parasite load in the myocardium, between Il18r1−/−, Myd88−/− and WT (B6) mice." (PMID 28895840, 2017). "Together, these results show that while increasing the numbers of IFN-γ+CD4+ T cells in Il18r1−/− mice is enough for restoring their resistance to infection to the WT level, both in terms of parasitemia and survival, this is not the case for Myd88−/− mice." (PMID 28895840, 2017).
psoriasis (5 papers, 2020 to 2023). An autoimmune condition characterized by red, well-delineated plaques with silvery scales that are usually on the extensor surfaces and scalp. "In this study, we verified the psoriasis susceptibility genes IFIH1 (2q24.3), ERAP2 (5q15), IL18R1 (2q12.1), LTBR (12p13.31), IL1RL1 (2q12.1), CARD14 (17q25.3), and SLC9A4 (2q12.1)." (PMID 36425068, 2022). "Other validated psoriasis susceptibility genes were ERAP2 (5q15), IL18R1 (2q12.1), LTB (12p13.31), IL1RL1 (2q12.1), CARD14 (17q25.3), and SLC9A4 (2q12.1)." (PMID 36425068, 2022).
eczema (4 papers, 2017 to 2024). "The only exception was that of IL-18R1, where high protein levels cause increased risk of allergy, hay fever, and eczema." (PMID 34878845, 2021). "In contrast, IL-18R1 increases the risk of developing allergy, hay fever, and eczema." (PMID 34878845, 2021). "IL4, IL13, IL1RL1, IL18R1 and TSLP are also the only proteins found to be common to eczema and rhinitis." (PMID 28598986, 2017).
leprosy (4 papers, 2013 to 2021). Leprosy is a chronic infectious disease affecting primarily the skin and peripheral nervous system. "A total of 5.7% (26/477) of the healthy subjects carried at least one missense allele while only 1.3% (7/551) of the leprosy cases displayed a nonsynonymous IL18R1 variant." (PMID 34879060, 2021). "Our results strongly argue against this possibility since loss of function mutations in IL18R1 are depleted in leprosy cases supporting the conclusion from the eQTL finding that reduced IL18 signalling is protective for leprosy." (PMID 34879060, 2021). "For example, the leprosy susceptibility allele of rs2058660 is associated with reduced IL18RAP expression in blood but increased expression of IL18R1 in the lung." (PMID 34879060, 2021). "In the context of leprosy, some immune response genes have already been investigated in genetic association studies, such as IL18R1, a gene that encodes the cytokine receptor interleukin (IL)-18, which has been associated as a risk factor for leprosy in a Chinese population." (PMID 34795692, 2021). "Rare amino acid changes in IL18R1 had also been identified in a case-control study of Chinese leprosy patients." (PMID 34879060, 2021). "We identified mutations in four genes (IL18R1, BCL10, CDSN, and PSORS1C2) as candidates for functional mediators of leprosy susceptibility." (PMID 34879060, 2021). "When we combined IL18R1 rare variants (MAF < 1%) detected in the Chinese and the Vietnamese population samples, significant depletion was maintained for rare variants in leprosy cases (PCAST = 0.001) surpassing multiple test correction." (PMID 34879060, 2021). "Using this approach, we observed a significant depletion of protein-altering variants in leprosy cases for the IL18R1 and BCL10 genes, identifying them as candidate genes for a protective role in leprosy pathogenesis." (PMID 34879060, 2021). "A significant depletion of protein-altering variants was detected for the IL18R1 and BCL10 genes in leprosy cases." (PMID 34879060, 2021). "While the depletion of rare amino acid changes for IL18R1 was detected for Vietnamese and Chinese leprosy cases, the reason for this depletion remains unknown." (PMID 34879060, 2021). "Taken together, these results directly implicated amino acid changes in IL18R1 and not its genomic neighbors as leprosy protective factors." (PMID 34879060, 2021). "At this stage of pathogenesis, blunted IL18 signalling in leprosy either by reduced IL18RAP expression or reduced IL18 binding by IL18R1 would hinder the development of anti-inflammatory host responses, which is expected to be beneficial for countering an infectious agent." (PMID 34879060, 2021). "Depletion of IL18R1 rare amino acid changes in leprosy cases of Asian descent." (PMID 34879060, 2021). "When testing the remaining 24 genes for enrichment or depletion of protein-altering variants in leprosy patients compared to healthy controls, the IL18R1 and the BCL10 genes displayed significant evidence for association with leprosy surpassing the multiple testing correction cut-off of P < 0.002." (PMID 34879060, 2021). "The IL18R1 gene is clustered with IL18RAP and IL1RL1 in the leprosy GWAS locus on chromosome 2q12.1." (PMID 34879060, 2021). "We found that the burden of amino acid changes in IL18R1 and BCL10 was significantly different between leprosy cases and healthy controls, suggesting these genes as functional candidates in leprosy pathogenesis." (PMID 34879060, 2021).
ulcerative colitis (4 papers, 2019 to 2024). An inflammatory bowel disease involving the mucosal surface of the large intestine and rectum. "IL18R1 has previously been found to have colocalized disease and eQTL association patterns in CD4 and CD8 cells for both ulcerative colitis and Crohn’s disease." (PMID 31727947, 2019).
viral infection (4 papers, 2011 to 2025). "Among the downregulated genes in activated CD8 T cells from Immune-Educated CLP mice was Il18r1 (downregulated 3.21 fold, P=0.0011), which is upregulated in effector CD8 T cells during acute viral infection and downregulated in exhausted CD8 T cells during chronic infection." (PMID 38562928, 2024).
atopic asthma (3 papers, 2009 to 2018). An asthma that is characterized by symptoms that are triggered by an allergic reaction caused by inhaled allergens such as dust mite allergen, pet dander, pollen and mold. "While IL18R1 and IL18RAP polymorphisms have been found associated with diseases such as schizophrenia, HSV1 seropositivity and atopic asthma, little is known about their contribution to CVD." (PMID 19473509, 2009).
Crohn disease (3 papers, 2020 to 2024). A gastrointestinal disorder characterized by chronic inflammation involving all layers of the intestinal wall, noncaseating granulomas affecting the intestinal wall and regional lymph nodes, and transmural fibrosis. "Similarly, risk alleles for T1D, such as Interleukin 27 (IL-27), Interleukin 10 (IL-10), and interleukin-18 receptor 1 (IL18RA), have been found to prevent Crohn’s disease." (PMID 39350769, 2024).
lung disease (3 papers, 2025). "Previous studies displayed that IL18R1 plays an important role in lung disease." (PMID 39847405, 2025). "Analysis of these data similarly demonstrated that IL18R1 expression was increased in the context of LRTI and pARDS, particularly in comparison to patients who were intubated due to neurologic failure but without diagnosed LRTI or lung disease (left)." (PMID 41285788, 2025).
sarcoidosis (3 papers, 2013 to 2022). Sarcoidosis is a multisystemic disorder of unknown cause characterized by the formation of immune granulomas in involved organs. "IL18R1 was highly expressed in severe viral and bacterial LRTI and SIRS, whereas CXCL10 was highly expressed in severe viral LRTI and in one of the sarcoidosis studies." (PMID 36561889, 2022).
chronic obstructive pulmonary disease (2 papers, 2019 to 2025). A chronic and progressive lung disorder characterized by the loss of elasticity of the bronchial tree and the air sacs, destruction of the air sacs wall, thickening of the bronchial wall, and mucous accumulation in the bronchial tree. "Analysis of the association between susceptibility of chronic obstructive pulmonary disease and single nucleotide polymorphism of IL18R1." (PMID 39847405, 2025).
melanoma (2 papers, 2021 to 2025). A malignant, usually aggressive tumor composed of atypical, neoplastic melanocytes. "IL18R1 expression also correlates with inflammation and high NLR (neutrophil/lymphocyte ratio) in melanoma, which validated the prognostic role of the inflammatory gene signature in addition to hematopoietic malignancies." (PMID 40255485, 2025). "However, CTXpre/CD4post-experienced Il18r1 KO mice showed similar therapeutic efficacy as C57BL/6 wild-type mice, implying that the anti-melanoma effect of highly tumor-specific IL-18Rαhi ex-T cells outweigh that of IL-18Rαhi en-T cells." (PMID 34493727, 2021).
multiple sclerosis (2 papers, 2020 to 2022). A progressive autoimmune disorder affecting the central nervous system resulting in demyelination. "An increased IL18R1 mRNA expression has been shown in both cerebrospinal fluid cells and PBMCs in multiple sclerosis." (PMID 32719716, 2020).
rheumatic disease (2 papers, 2022 to 2024). "Additionally, a further polymorphism in IL18R1 at chr2_103013408 seems to have a protective influence against the rheumatic diseases under investigation." (PMID 38675400, 2024).
Splenomegaly (2 papers, 2023 to 2024). Abnormal increased size of the spleen. "Analysis of IkkeK38A/K38ATbk1fl/D135NCx3cr1-Crewt/tgIl1.18.33r-/- revealed that combined IL-1R1, IL-18R1 and IL-33R deficiency ameliorated splenomegaly, granulocytosis, and monocytosis, revealing an important role for IL-1, IL-18, and IL-33 in driving systemic inflammation in these animals." (PMID 38167258, 2024).
systemic sclerosis (2 papers, 2022 to 2024). A chronic disorder, possibly autoimmune, marked by excessive production of collagen which results in hardening and thickening of body tissues. "The polymorphisms identified in ACE2 (chrX_15596143), IL-18 (chr11_112014152), IL-18R1 (chr2_103013408), IFNGR1 (chr6_137519588), and IL-2 (chr4_123377482) genes can be considered predisposing factors for the onset of systemic sclerosis." (PMID 38675400, 2024).
thymoma (2 papers, 2010 to 2024). A neoplasm arising from the epithelial cells of the thymus. "Patients with hyperplasia and thymoma differed in several proteins, including IL-18R1, TRAIL, CCL23, CX3CL1, CD8A, IL-8, TNF-β, and CCL11." (PMID 39165841, 2024).
tuberculosis (2 papers, 2014 to 2020). A chronic, recurrent infection caused by the bacterium Mycobacterium tuberculosis. "In addition, the age-dependent predisposition to TB conferred by IL18R1 genotypes adds to the explanations for why mice deficient in the IL-18 receptor were not more susceptible to M. tuberculosis when compared to wild-type mice without considering age effects." (PMID 25360588, 2014).
allergic conjunctivitis (1 paper, 2025). "Differential expression of Il18r1 and Il18rap in the allergic conjunctivitis mouse model conjunctiva (scRNA-seq)." (PMID 41476961, 2025).
Alzheimer disease (1 paper, 2024). A progressive, neurodegenerative disease characterized by loss of function and death of nerve cells in several areas of the brain leading to loss of cognitive function such as memory and language. "Furthermore, recent studies suggest certain inflammatory markers, such as IL18R1, demonstrate a causal relationship with both IBD and pathologies of the aging brain, such as Alzheimer’s disease, further demonstrating a link between IBD and aging brain function." (PMID 38356645, 2024).
anaphylaxis (1 paper, 2022). An acute hypersensitivity reaction that occurs from exposure to an allergen. "Genetic variations at the IL-18 locus (IL18R1 and IL18RAP) were associated with exercise-induced anaphylaxis, while MMP9 and OSM provide evidence for the involvement of innate immune pathways." (PMID 36569939, 2022).
breast carcinoma (1 paper, 2022). "Furthermore, the IL18R1 expression level is positively associated with the disease-free survival (DFS) of triple-negative patients with breast cancer." (PMID 36544782, 2022).
cerebral malaria (1 paper, 2025). A sequestration of Plasmodium falciparum in the brain, which can cause coma and/or seizures. "The most significant transcript uniquely associated with cerebral malaria was IL18R1." (PMID 40383794, 2025).
coronary artery disease (1 paper, 2021). "The single nucleotide polymorphism of the IL18R1 gene has been found in cardiovascular disease, such as coronary artery disease." (PMID 34336943, 2021).
cyst (1 paper, 2020). A sac-like closed membranous structure that may be empty or contain fluid or amorphous material. "Significant increases in mRNA levels for ICOS, CXCR3, CXCR6, IL-18R1, and Chil3 were detectable during cyst elimination by perforin-dependent anticyst activity of CD8+ T cells initiated at 6 weeks after infection." (PMID 32291349, 2020).
dengue (1 paper, 2023). "For instance, CIITA continues to be important by providing resistance factors to modern infectious diseases such as Ebola virus and SARS-CoV-2, and IL18R1 has been shown to confer protection against more severe clinical dengue phenotypes through IL1α downregulation." (PMID 36726304, 2023).
dermatomyositis (1 paper, 2022). Dermatomyositis (DM) is a type of idiopathic inflammatory myopathy characterized by evocative skin lesions and symmetrical proximal muscle weakness. "RT-qPCR and western blot further validated IL18R1 was upregulated in the muscle tissues of dermatomyositis." (PMID 35517781, 2022).
gout (1 paper, 2023). A condition characterized by painful swelling of the joints, which is caused by deposition of urate crystals. "The IL-1 signaling member IL-18 and its receptor IL-18R1 and the IL-6 family of cytokines members IL-6, LIF-R, and OSM were also elevated in AH, which is in line with major studies implicating IL-1-driven inflammation and IL-6 signaling in the pathogenesis of gout." (PMID 37810213, 2023).
hay fever (1 paper, 2021). "Apart from LT-α, all results from the main analysis replicated (FDR < 0.05) in all settings where the analysis was feasible, with the one exception being the effect of IL-18R1 on hay fever, which was only nominally significant in one of the stricter settings." (PMID 34878845, 2021). "IL-18R1 showed harmful effects on several diseases: hay fever (OR = 1.02, 95% CI = 1.01 to 1.03; fig." (PMID 34878845, 2021).
Headache (1 paper, 2025). Cephalgia, or pain sensed in various parts of the head, not confined to the area of distribution of any nerve. "Among these associations, 108 proteins were associated with headache, of which C4BPB (odds ratio [OR] = 1.59, P = 1.67 × 10−39), IL18R1 (OR = 1.55, P = 7.36 × 10−25), and CDHR5 (OR = 1.46, P = 6.31 × 10−23) had the strongest associations." (PMID 40048323, 2025).
liver cancer (1 paper, 2020). An epithelial or non-epithelial malignant neoplasm that arises from the liver. "Similarly, an increase of IL-18R1 reduced tumor burden in liver cancer mouse models." (PMID 33239635, 2020).
liver fibrosis (1 paper, 2025). "In chemically induced liver fibrosis, IL-18 receptor (Il18r1) was found to be highly expressed in a subset of activated HSCs, but not in quiescent HSCs." (PMID 41275524, 2025).
lymphopenia (1 paper, 2021). Reduction in the number of lymphocytes. "In addition, anti-IL-18, Il18r1 KO, Foxp3DTR, and Rag1 KO mice were also analyzed to investigate the effect of IL-18 signaling, regulatory T-cell (Treg) depletion, and permanent lymphopenia." (PMID 34493727, 2021).
mastitis (1 paper, 2025). Inflammation of breast tissue during lactation or postpartum due to an obstructed duct or infection. "In both S. aureus-positive and S. chromogenes-positive cows, the DE snoRNAs were correlated with several immune and inflammatory genes (e.g., IL1R, IL18R1, STAT3, NFKB2, MYD88, VEGFA and CD40), all of which have been reported in several studies to be associated to mastitis." (PMID 40936092, 2025).
osteosarcoma (1 paper, 2022). A usually aggressive malignant bone-forming mesenchymal neoplasm, predominantly affecting adolescents and young adults. "Intriguingly, the mRNA expression level of interleukin-18 receptor 1 (IL18R1) was significantly higher in osteosarcoma cell lines than in hFob1.19 normal osteoblast cell line, implying that osteosarcoma cells are more sensitive to IL-18 than normal bone cells." (PMID 36274066, 2022).
Parkinson disease (1 paper, 2025). A progressive degenerative disorder of the central nervous system characterized by loss of dopamine producing neurons in the substantia nigra and the presence of Lewy bodies in the substantia nigra and locus coeruleus. "In summary, the IL18R1 biomarker screened acts as an inflammatory gene that may influence the progression of Parkinson’s disease." (PMID 40435035, 2025).